TUBB4A (tubulin beta 4A class IVa)
Description:
Tubulin is the major constituent of microtubules, a cylinder consisting of laterally associated linear protofilaments composed of alpha- and beta-tubulin heterodimers. Microtubules grow by the addition of GTP-tubulin dimers to the microtubule end, where a stabilizing cap forms. Below the cap, tubulin dimers are in GDP-bound state, owing to GTPase activity of alpha-tubulin.
Synonyms: TUBB4; beta-5; DYT4
Tractability: Small molecule: an approved drug acts on it; a high-quality ligand is known; it belongs to a druggable protein family. PROTAC: ubiquitination databases record sites on it; its protein half-life has been measured; a small molecule that binds it is known. Other modalities: an approved drug acts on it.
Target class: Structural protein
Gene: Protein-coding gene on chromosome 19 (6,494,319 to 6,502,848, reverse strand). Ensembl gene ENSG00000104833.
Subcellular location: Cytoplasm, cytoskeleton
Subcellular location (Human Protein Atlas): Microtubules; Basal body; Cytokinetic bridge; End piece; Flagellar centriole; Mitotic spindle; Primary cilium; Primary cilium tip; Principal piece
Pathways (Reactome):
Cell Cycle: AURKA Activation by TPX2; EML4 and NUDC in mitotic spindle formation; Loss of Nlp from mitotic centrosomes; Loss of proteins required for interphase microtubule organization from the centrosome; Mitotic Prometaphase; Recruitment of NuMA to mitotic centrosomes; Recruitment of mitotic centrosome proteins and complexes; Regulation of PLK1 Activity at G2/M Transition; Resolution of Sister Chromatid Cohesion; Sealing of the nuclear envelope (NE) by ESCRT-III; Separation of Sister Chromatids; The role of GTSE1 in G2/M progression after G2 checkpoint
Vesicle-mediated transport: COPI-dependent Golgi-to-ER retrograde traffic; COPI-independent Golgi-to-ER retrograde traffic; COPI-mediated anterograde transport; Gap junction assembly; Microtubule-dependent trafficking of connexons from Golgi to the plasma membrane; Translocation of SLC2A4 (GLUT4) to the plasma membrane
Metabolism of proteins: Carboxyterminal post-translational modifications of tubulin; Formation of tubulin folding intermediates by CCT/TriC; Post-chaperonin tubulin folding pathway; Prefoldin mediated transfer of substrate to CCT/TriC
Organelle biogenesis and maintenance: Anchoring of the basal body to the plasma membrane; Cargo trafficking to the periciliary membrane; Intraflagellar transport
Signal Transduction: Hedgehog 'off' state; RHO GTPases Activate Formins; RHO GTPases activate IQGAPs
Immune System: MHC class II antigen presentation; PKR-mediated signaling
Neuronal System: Activation of AMPK downstream of NMDARs; Assembly and cell surface presentation of NMDA receptors
Autophagy: Aggrephagy
Cellular responses to stimuli: HSP90 chaperone cycle for steroid hormone receptors (SHR) in the presence of ligand
Developmental Biology: Recycling pathway of L1
Disease: HCMV Early Events
Hemostasis: Kinesins
Gene Ontology:
Molecular function: calcium ion binding; protein binding; GTP binding; structural constituent of cytoskeleton; GTPase activity
Biological process: negative regulation of microtubule polymerization; mitotic cell cycle; cytoskeleton organization; microtubule-based process
Cellular component: axoneme; ciliary tip; cilium; extracellular exosome; intercellular bridge; microtubule; microtubule cytoskeleton; mitotic spindle; nucleus; sperm end piece; sperm principal piece; cytosol; cytoplasm; cytoskeleton; internode region of axon; myelin sheath; neuronal cell body
Genetic constraint (gnomAD): Loss-of-function variants: 13 observed, 34.2 expected, observed/expected ratio (o/e) 0.38, 90% interval 0.25 to 0.6. The upper end of that interval is the gene's LOEUF score, 0.6, which puts it in group 2 of 6, group 1 being the genes least tolerant of losing a copy. Missense variants: 299 observed, 659.93 expected, observed/expected ratio (o/e) 0.45, 90% interval 0.41 to 0.5. Synonymous variants: 279 observed, 279.89 expected, observed/expected ratio (o/e) 1, 90% interval 0.9 to 1.1.
Gene-disease validity (ClinGen):
ClinGen rates the evidence that TUBB4A causes each of these diseases.
TUBB4A-related neurologic disorder (autosomal dominant): Definitive. Any neurologic condition in which the cause of the disease is a mutation in the TUBB4A gene.
Homologues: Orthologues: chimpanzee TUBB4A (100% identical), dog TUBB4A (100% identical), macaque TUBB4A (100% identical), mouse Tubb4a (100% identical), rat Tubb4a (100% identical), pig TUBB4A (99% identical), guinea pig TUBB4A (97% identical), rabbit TUBB4A (90% identical). Paralogues in human: TUBB4B (99% identical), TUBB (96% identical), TUBB2B (96% identical), TUBB2A (95% identical), TUBB3 (92% identical), TUBB6 (92% identical), TUBB8 (90% identical), TUBB8B (88% identical), TUBB1 (79% identical), TUBA1B (44% identical), TUBA1A (43% identical), TUBA1C (43% identical), and 11 more.
Diseases named in the same sentence as TUBB4A in open-access papers:
TUBB4A is named in the same sentence as 79 diseases in open-access papers, as found by Europe PMC text mining. Sharing a sentence is not in itself a finding about the gene and the disease. The quoted sentences say what the papers report.
Dystonia (17 papers, 2006 to 2025). An abnormally increased muscular tone that causes fixed abnormal postures. "In contrast, the TUBB4A mutants p.Arg2Gly and p.Ala271Thr that cause dystonia 4 (DYT4) suppressed neurite extension in neuroblastoma and disorganized microtubule network in cells." (PMID 37755363, 2023). "Only 7 of these articles, including ours, described cases with mutations in the TUBB4A gene and a phenotype consistent with dystonia, after exclusion of articles reporting on H‐ABC and spastic paraplegia." (PMID 35844288, 2022). "Nevertheless, TUBB4A mutations remain an exceedingly rare cause of laryngeal or other isolated dystonia and regular screening of TUBB4A mutations for isolated dystonias has a very low yield." (PMID 35844288, 2022). "TUBB4A mutations have been initially described as a cause of whispering dysphonia (DYT4 dystonia), but have subsequently been reported as a cause of HSP." (PMID 33646413, 2021). "A 44 year old man with a p.Arg2Gly variant in TUBB4A was found to have an improvement in dystonia (55% reduction in BFMDRS) with a more prominent improvement in cervical and facial dystonia with bilateral GPi-DBS." (PMID 33488508, 2020). "With the recent identification of TUBB4A as the cause of whispering dysphonia, the function of several genes now point to cell structure as playing an important role in dystonia." (PMID 23775978, 2013). "DYT-TUBB4A (dystonia 4, DYT4, OMIM# 128101), also known as “whispering dysphonia”, is a distinct form of dystonia caused by pathogenic variants in TUBB4A, a gene located on chromosome 19p13." (PMID 40724495, 2025). "A recent study identified novel TUBB4A mutants, including p.Asp295Asn, p.Arg46Met, p.Gln424His, and p.Arg121Trp, in patients with dystonia from four families; via in silico analysis, the function of these mutants was similar to that of the p.Arg2Gly mutant." (PMID 37755363, 2023). "Other genes found to be associated with isolated or combined dystonia include ANO3 (DYT24), TUBB4A (DYT4), GCH1 (DYT5a), TH (DYT5b), TAF1 (DYT3), PRKRA (DYT16), ATP1A3 (DYT12), SGCE (DYT11), KCTD17, and CACNA1A." (PMID 33051750, 2021). "TUBB4A‐related disorder is an exception as it often manifests with severe dystonia." (PMID 40590574, 2025). "There is a single case report documenting the response to DBS in TUBB4A-related dystonia." (PMID 33488508, 2020). "We screened a number of autosomal dominant dystonia families and dystonia brains collected at our institute for TUBB4A mutations, and although no other mutations were identified, it will be important to analyze this gene in other similar pedigrees." (PMID 23424103, 2013). "Additionally, likely pathogenic or pathogenic variants were found in ATP1A3 (n = 5) and GNAO1 (n = 1) for genes causing combined dystonia, as well as ACTB (n = 1), IRF2BPL (n = 1), SPR (n = 1), and TUBB4A (n = 3) for genes linked to dystonia with other neurological or systemic features." (PMID 40533913, 2025). "Sequencing of the other known PTD genes (THAP1, TUBB4a, CIZ1, ANO3, and GNAL) should be considered in patients with predominant cranial-cervical and laryngeal involvement, especially if family history is positive, with prioritization according to the age at onset and distribution of dystonia." (PMID 23596437, 2013).
leukodystrophy (13 papers, 2020 to 2026). Leukodystrophies are a group of rare, progressive, metabolic, genetic diseases that affect the brain, spinal cord and often the peripheral nerves. "Pathogenic variants of TUBB4A are implicated in paediatric-onset leukodystrophies, affecting myelin development." (PMID 41488750, 2025). "Control Cohort 1 includes 166 samples with non-AGS leukodystrophies (e.g., POLR3-related leukodystrophy, Pelizaeus Merzbacher disease, TUBB4A-associated leukodystrophies, and Alexander disease)." (PMID 38885315, 2024). "T178M has also been reported in TUBB2A (causing nervous system abnormality) and TUBB4A (causing hypomyelinating leukodystrophy)." (PMID 37600020, 2023). "The R262H substitution has also been reported in TUBB2A (causing arthrogryposis multiplex congenita) and TUBB4A (causing hypomyelinating leukodystrophy)." (PMID 37600020, 2023). "Of note, the E410K substitution has also been reported in the TUBB4A isotype (causing torsion dystonia, hypomyelinating leukodystrophy, spastic paraparesis) and in the TUBB8 isotype (causing male infertility)." (PMID 37600020, 2023). "The identification of mutations in tubulin beta class IVA (TUBB4A) in hypomyelination with atrophy of the basal ganglia and cerebellum, a type of leukodystrophy, prompted us to elucidate the role of TUBB4A in OLGs." (PMID 34658775, 2021). "Hypomyelination with Atrophy of Basal Ganglia and Cerebellum (H-ABC) is a leukodystrophy caused by sporadic, typically de novo, heterozygous mutations in the TUBB4A gene." (PMID 32463361, 2020). "Mutations in TUBB4A result in a spectrum of leukodystrophy including Hypomyelination with Atrophy of Basal Ganglia and Cerebellum (H-ABC), a rare hypomyelinating leukodystrophy, often associated with a recurring variant p.Asp249Asn (D249N)." (PMID 32463361, 2020). "Mutations in TUBB4a have been associated with hypomyelination, including cerebellar atrophy, hereditary dystonia, hereditary spastic paraplegia, and epileptic encephalopathy associated with hypomyelinated leukodystrophy." (PMID 41488750, 2025). "Comparing the structural features of brain development in these patients with a previously reported hypomyelinating leukodystrophy linked to an analogous T178M mutation in the TUBB4A isotype suggests specific developmental requirements for each β-tubulin isotype." (PMID 34869359, 2021). "Examples discussed in this review include TUBB4A-related leukodystrophy and leukoencephalopathy with brainstem and spinal cord involvement and lactate elevation." (PMID 41315317, 2025). "Recently, our research group demonstrated that taiep rats have a point mutation in Tubb4a gen and its corresponding protein TUBB4A (OMIM 602662), with pathological characteristics similar to the human leukodystrophy hypomyelination with atrophy of the basal ganglia and cerebellum (H-ABC);." (PMID 38427650, 2024). "Tubulin beta 4A class IVa (TUBB4A, OMIM *602662), which is a member of the beta tubulin family, a subunit of microtubules, is reported to cause AD Dystonia 4, torsion (OMIM #128101) and AD Leukodystrophy, hypomyelinating, 6 (OMIM #612438)." (PMID 36672520, 2022). "Ninety-nine caregivers (of 46 females and 53 males, mean age = 7 years 11 months, age range = 2 months-34 years) completed the PEDI-CAT (Aicardi-Goutières syndrome n = 52, TUBB4A-related leukodystrophies n = 22, Pelizaeus-Merzbacher disease n = 7, POLR3-related leukodystrophy n = 18)." (PMID 42060827, 2026).
whispering dysphonia (8 papers, 2006 to 2025). "A p.(Arg2Gly) mutation in TUBB4A has been identified in a family with dystonia type 4 (‘Whispering dysphonia’)." (PMID 30087272, 2018). "In one large Australian family with fully penetrant juvenile-adult-onset “whispering dysphonia,” occasional generalization and alcohol benefit, the p.R2G mutation in the TUBB4a gene (DYT4, encoding the isoform a of b-Tubulin) has been identified by exome sequencing." (PMID 23596437, 2013).
tubulinopathies (7 papers, 2020 to 2025). "Mutations in seven genes encoding α- (TUBA1A), β- (TUBB2A, TUBB2B, TUBB3, TUBB4A, TUBB5), and γ- (TUBG1) microtubulin are linked to extensive overlapping brain malformations or tubulinopathies." (PMID 40948494, 2025). "It is worth specifying that tubulinopathies are, to this date, the pathological manifestation of mutations in the genes of a just a subset of tubulin genes: TUBB2A, TUBB2B, TUBB3, TUBG1, TUBA8, TUBB, TUBA3E, and TUBB4A." (PMID 32581692, 2020). "We identified a TUBB6 p.(Glu410Lys) variant in syndromic familial ptosis pedigree ENG_CML; this substitution has been reported as P/LP for tubulinopathies in four paralogs (TUBB2A, TUBB2B, TUBB3, and TUBB4A; ClinVar Variation IDs: 986830, 1195195, 6967, 135658)." (PMID 38585811, 2024).
melanoma (6 papers, 2023 to 2026). A malignant, usually aggressive tumor composed of atypical, neoplastic melanocytes. "TUBB4A is significantly upregulated in the responding group, and has been linked to melanoma‐associated pathways in a previous study, suggesting its potential as a treatment response marker." (PMID 40420636, 2026). "Among other five TRGs, TUBB4A serves as a tumor-promoting factor in several tumor types including melanoma and prostate cancer, and ELOVL3 is considered as a risk gene in hepatocellular carcinoma." (PMID 37976136, 2023). "TUBB4A is also highly expressed in human prostate cancer and melanoma cells, and TUBB4A knockout results in reduced cell growth and migration." (PMID 38704483, 2024). "The Kaplan–Meier analysis showed that five upregulated genes were significantly related to both the OS and DFS of melanoma patients, including TUBB4A, PSEN2, SLC45A2, QPRT, and TRPV2." (PMID 37439014, 2023). "TUBB4A functions as a driver in increasing melanoma cell proliferation and motility, and TUBB4A inhibitor agents can significantly induce melanoma cell apoptosis and G2/M cell cycle arrest." (PMID 37439014, 2023). "TUBB4A knockdown by siRNA significantly inhibited the proliferation and metastasis of A375 and B16-F10 melanoma cells." (PMID 37439014, 2023). "The experimental results showed that knockdown of TUBB4A inhibited the proliferation and migration of A375 and B16-F10 melanoma cells." (PMID 37439014, 2023). "Here, we for the first time verified the role of TUBB4A in melanoma." (PMID 37439014, 2023). "The coexpressed genes with TUBB4A were enriched in melanoma-related pathways and functions." (PMID 37439014, 2023). "Moreover, our in vitro experiments showed that TUBB4A knockdown reduced the migration and proliferation of melanoma cells." (PMID 37439014, 2023). "Through the TGFβ signaling axis and other cytokine pathways, HOXA1 may regulate TUBB4A to drive melanoma growth and metastasis, which should be proven by experimental studies in the future." (PMID 37439014, 2023). "In summary, TUBB4A may serve as a novel therapeutic target for treating melanoma." (PMID 37439014, 2023). "TUBB4A may be a potential prognostic marker and therapeutic target of melanoma." (PMID 37439014, 2023). "Moreover, TUBB4A overexpression was found in melanoma tissues in all three datasets." (PMID 37439014, 2023). "TUBB, TUBB1, TUBB2A, TUBB4A and TUBB4B belong to the tubulin family, and gene expression analyses showed a higher expression of all these tubulins in melanoma compared to normal skin." (PMID 37291228, 2023). "We demonstrated that TUBB4A was highly expressed in SKCM, and its expression level was positively related to the viability of melanoma cells." (PMID 37439014, 2023). "Two TUBB4A inhibitors, DHA and Nocodazole, promoted melanoma cell apoptosis and induced cell cycle arrest in the G2/M phase in vitro." (PMID 37439014, 2023). "Two small-molecule inhibitors of TUBB4A, Dihydroartemisinin (DHA) and Nocodazole, were used to validate the effect of TUBB4A on the apoptosis and cell cycle of melanoma cells." (PMID 37439014, 2023). "However, the potential function of TUBB4A in melanoma has not been reported to date." (PMID 37439014, 2023).
Ataxia (4 papers, 2019 to 2025). Ataxia refers to impaired coordination of voluntary muscle movement. "We also analyzed the co-expression network of those ataxia risk genes and revealed a central role of Eef2, Grid2, Tubb4a in the co-expression networks, while Ttbk2 and Bean1 have few interactions with other ataxia risk genes." (PMID 30690467, 2019). "Hypomyelination with atrophy of the basal ganglia and cerebellum (H-ABC) is a central neurodegenerative disease due to mutations in the tubulin beta-4A (TUBB4A) gene, characterized by motor development delay, abnormal movements, ataxia, spasticity, dysarthria, and cognitive deficits." (PMID 34335454, 2021). "TUBB4A-related leukodystrophy (TUBB4A-LD), also known as hypomyelination with atrophy of the basal ganglia and cerebellum (H-ABC), is a disorder dominated by extrapyramidal signs, cerebellar ataxia, and spasticity." (PMID 41315317, 2025).